STAT3 (signal transducer and activator of transcription 3)
Diseases named in the same sentence as STAT3 in open-access papers (continued):
Sharing a sentence is not in itself a finding about the gene and the disease.
non-small cell lung carcinoma (277 papers, 2007 to 2026). A group of at least three distinct histological types of lung cancer, including non-small cell squamous cell carcinoma, adenocarcinoma, and large cell carcinoma. "Preclinical evidence suggests the feedforward cytokine loop of interleukin-6/Janus kinases (JAK)/STAT3 plays a role in epidermal growth factor receptor tyrosine kinase inhibitor (EGFR TKI) resistance in EGFR-mutated non-small cell lung cancer (NSCLC)." (PMID 34773474, 2022). "Constitutively activated STAT3 has been associated with the pathogenesis of not only non-small cell lung cancer but in almost 70% of cancer types." (PMID 35928273, 2022). "Persistent activation of STAT3 is frequently observed in non-small cell lung cancer and is associated with a poor prognosis." (PMID 34944848, 2021). "The activation of STAT3 is associated with cell proliferation and the inhibition of apoptosis in breast and non-small cell lung cancer." (PMID 34721022, 2021). "The JAK2/STAT3 signaling pathway has been reported to be closely associated with the development and metastasis of non-small-cell lung cancer." (PMID 33195699, 2020). "A higher level of phosphorylated STAT3 (active STAT3) contributed to epithelial-to-mesenchymal transition (EMT) as well as increased CSC-like phenotypes of non-small cell lung cancer cells (NSCLCs), while the inhibition of STAT3 caused the opposite effects." (PMID 31861050, 2019). "Limited studies by us and others have suggested that ALDH1A3 supports stemness in GSCs by promoting glycolysis/gluconeogenesis, and is associated with higher Stat3 signaling in ALDH1+ CSCs derived from non-small cell lung cancer." (PMID 28423611, 2017). "Many studies have investigated the correlation between p-STAT3 and malignant tumors; for example, studies confirmed that high p-STAT3 expression was associated with poor prognosis among patients with non-small-cell lung cancer." (PMID 27504822, 2016). "STAT3 is constitutively active and associated with poor clinical prognosis in non-small cell lung carcinoma (NSCLC), B-cell lymphoma and ovarian cancer." (PMID 24657910, 2014). "Meanwhile, Nobiletin resist immune evasion by modulating miR-197/STAT3/PD-L1 signalling in non-small cell lung cancer (NSCLC) cells." (PMID 41579221, 2026). "Phosphodiesterase 1A (PDE1A) promotes the metastasis of non-small cell lung cancer (NSCLC) cells via the STAT3 signaling pathway." (PMID 40704992, 2025). "Therapeutic agents targeting the IL-6/STAT3 pathway have shown promise in the treatment of non-small cell lung cancer and are poised to emerge as efficacious interventions in this domain." (PMID 40426998, 2025). "It is noteworthy that the latest report has revealed that FXR promotes non-small-cell lung cancer metastasis by activating the Jak2/STAT3 signaling pathway through the transactivation of the IL6ST and IL6 genes." (PMID 39940889, 2025). "The deubiquitinating enzyme USP28 mediates STAT3 signaling in non-small-cell lung cancer cells, and USP28 interacts with STAT3 and enhances its stability by inducing the deubiquitination of STAT3." (PMID 39773987, 2025). "Previous literature has shown that IL-37 inhibits invasion and metastasis in non-small cell lung cancer by suppressing the IL-6/STAT3 signaling pathway." (PMID 40444012, 2025). "Metastasis-associated lung adenocarcinoma transcript 1 (MALAT1) significantly upregulates MRP1 and MDR1 by activating STAT3 in cisplatin (DDP) resistant non-small cell lung cancer." (PMID 41145465, 2025). "In terms of mechanism, CAF secretes MMPs through activation of STAT3, thereby promoting osimertinib resistance in non-small cell lung cancer." (PMID 40703348, 2025). "For example, activation of Akt1 increased the expression of IL-6, thereby promoting the phosphorylation and activation of Stat3 in non-small cell lung cancer (NSCLC) cells." (PMID 41415834, 2025).
non-small cell lung carcinoma (continued). "Signal Transducer and Activator of Transcription 3 (STAT3) revival has been observed in non-small cell lung cancer (NSCLC) patient samples." (PMID 39113883, 2024). "In this study, we demonstrated that DH_31 inhibits migration, anoikis resistance, and downregulates the protein expression of STAT3 and its downstream targets involved in metastasis in non-small cell lung cancer." (PMID 39195486, 2024). "For instance, BAs activate the FXR receptor, thereby promoting the metastasis of non-small cell lung cancer (NSCLC) by mediating the JAK2/STAT3 signaling pathway through the transactivation of IL-6ST and IL-6 genes." (PMID 39769418, 2024). "In terms of mechanism, IGFBP2/ITGA5 enhances the expression of CXCL1 by activating STAT3, thereby promoting gefitinib resistance in non-small cell lung cancer." (PMID 38918360, 2024). "ALKBH5 promotes non-small cell lung cancer progression by regulating cancer and tumor-associated macrophage behavior through the JAK2/p-STAT3 pathway and the expression of CCL2 and CXCL10, respectively." (PMID 38872221, 2024). "Promoted angiogenesis by stimulating VEGF production of cancer cells via the STAT3/GIV signaling pathway in non-small-cell lung cancer." (PMID 39906741, 2024). "JAK2 was identified as a target of ALKBH5-mediated m6A modification, which activates the JAK2/p-STAT3 pathway to promote non-small cell lung cancer progression." (PMID 38872221, 2024). "Blocking IL-6/STAT3 signal transduction can significantly inhibit tumor growth and STAT3 phosphorylation in mice xenografts with non-small cell lung cancer." (PMID 36990991, 2023). "Over the last years however, CXCL12-induced JAK2/STAT3 signaling in human non-small-cell lung cancer cells and JAK2/STAT3 and JAK3/STAT6 signaling in a human proximal tubular cell line was demonstrated." (PMID 36725964, 2023). "For instance, loss of USP28 in nude mice resulted in delayed tumor growth of non-small cell lung cancer, which was mediated by the attenuation of STAT3 (a molecule that can be deubiquitinated by USP28) signaling." (PMID 36879346, 2023). "Niclosamide’s potential in non-small cell lung cancer (NSCLC) is evident as it effectively inhibits STAT3 phosphorylation and PD-L1 expression in a dose- and time-dependent manner." (PMID 37627178, 2023). "Constitutive activation of STAT3 was observed in more than 50% of non-small-cell lung carcinoma (NSCLC) patients and correlated with tumor lymph node metastasis, drug resistance, advanced clinical stage and low level of tumor differentiation." (PMID 38137415, 2023). "Alike, it was revealed that miR-30e-5p depletes the occurrence of non-small cell lung cancer by downregulating ubiquitin-specific peptidase 22 and affecting the sirtuin 1/Janus kinase/signal transducer and activator of transcription 3 signaling pathway." (PMID 35300562, 2022). "By regulating the JAK/STAT3 signaling pathway and downstream apoptotic molecules, some researchers revealed that GA had independent anticancer effects in non-small-cell lung cancer A549 cells and aided the anticancer effects of cisplatin." (PMID 35408583, 2022). "Recently, a comprehensive study in non-small cell lung cancer demonstrated that reduction in STAT3 in the tumor microenvironment using an antisense oligonucleotide reversed immunotherapy resistance in preclinical STK11 knockout mouse models." (PMID 35267462, 2022). "Then the combination of heteronemin and tetrac (or NDAT) downregulates EGFR/STAT3 expressions and cell motility in KRAS mutated A549 non-small cell lung cancer (NSCLC) cells." (PMID 35705962, 2022). "The chemotherapeutic sensitivity of OSM against non-small cell lung cancer cells was increased when STAT3 was suppressed by chemically modified siRNAs." (PMID 35745729, 2022). "A recent study has shown that STAT3 activation induced by TESC can upregulate the expression of ALDH1 in non-small cell lung cancer, suggesting that TESC can also potentially induce the upregulation of ALDH1." (PMID 35173149, 2022).
non-small cell lung carcinoma (continued). "miR-9600 enhanced the drug sensitivity of non-small cell lung cancer to paclitaxel and cisplatin by inhibiting targeted STAT3." (PMID 35721082, 2022). "Previous research has demonstrated the importance of tumor cell-intrinsic and extrinsic STAT3 signaling, as these activities encourage angiogenesis in non-small cell lung cancer by upregulating the expression of VEGF and other growth factors." (PMID 35884919, 2022). "Receptor tyrosine kinases, including EGFR, regulate cell survival in human non-small cell lung cancer (NSCLC) via STAT3 activation." (PMID 36055997, 2022). "A recent study reported that IL-6 can induce EMT of non-small cell lung cancer cells by STAT3 activation and insulin-like growth factor-1 receptor (IGR-1R)." (PMID 34064322, 2021). "In another recent study, it was demonstrated that miR-130a targets STAT3 to increase the cytotoxic activity of NK cells against non-small cell lung cancer (NSCLC) cells." (PMID 34680611, 2021). "We also knocked down or knock out STAT3 in A549 cells to examine the anti-cancer actions of W214-S in non-small cell lung cancer." (PMID 33391507, 2021). "In 2017, the n-hexane extract of Taiwanofungus camphoratus exhibited inhibitory activity on STAT3 pathways in EGFR wild-type NSCLC (non-small cell lung cancer) cells." (PMID 34577615, 2021). "In non-small-cell lung cancer, fraxetin displayed antiproliferation effects and induced cell cycle arrest by blocking STAT3." (PMID 33477262, 2021). "Subsequently, studies suggested that overexpression of KLF7 regulated cell growth and progression by mediating STAT3-induced lncRNA LINC00668 in non-small-cell lung cancer, and contributed to squamous carcinoma progression." (PMID 33858520, 2021). "It was previously demonstrated by members of our laboratory that PD-L1 is controlled by the miR-197/STAT3/CKS1B network in non-small-cell lung cancer." (PMID 33467725, 2021). "The high expression of NKCC1 promoted EMT metastasis by activating the STAT3 signaling pathway in non-small-cell lung cancer." (PMID 32211242, 2020). "TNK2-AS1/STAT3 promotes STAT3 signaling, leading to angiogenesis in non-small cell lung cancer via the induction of VEGFA." (PMID 33050646, 2020). "In our previous study, we found IL-37 can inhibit cell invasion and metastasis through the IL-6/STAT3 signaling in non-small cell lung cancer (NSCLC)." (PMID 33489865, 2020). "A cEt ASO targeting the transcription factor STAT3 has shown robust single-agent activity in highly treatment-refractory lymphoma and non-small cell lung cancer studies." (PMID 33353933, 2020). "For example, IL-6 produced by TAMs supported the expansion and drug resistance of CSCs through STAT3 signaling in non-small-cell lung cancer (NSCLC) and HCC." (PMID 32117287, 2020). "In a phase I clinical trial non-small cell lung cancer (NSCLC) patients treated with the STAT3 inhibitor OPB-51602 where shown to have a better response to therapy." (PMID 32194856, 2020). "Inhibition of COX2/PGE2 pathway can effectively suppress tumor growth, EMT and metastasis of non small cell lung cancer or extrahepatic cholangiocarcinoma through PLA2G4A/PGE2/STAT3 pathway." (PMID 32546278, 2020). "Aldo-keto reductase family 1 member C1 (AKR1C1) promotes malignancy of Non-Small Cell Lung Cancer (NSCLC) by activating Signal Transducer and Activator of Transcription 3 (STAT3) pathway." (PMID 32104503, 2020). "Phase I testing of OPB-51602 demonstrated reduction of phosphorylated STAT3 in monocytic cells and regression of tumors in two patients with non-small cell lung cancer." (PMID 31671769, 2019). "Downregulation of IL-6/JAK/STAT3 pathway activation subsequently reduces the expression of PD-L1 in non-small cell lung cancer." (PMID 31533774, 2019). "CXCR4+ non-small cell lung cancer (NSCLC) cells are strong examples of tumorigenic stem-like cancer cells that maintain stemness through the CXCR4-mediated STAT3 pathway." (PMID 31752959, 2019).
non-small cell lung carcinoma (continued). "Diosgenin exerts its tumor suppressive function to induce apoptosis by down-regulating MALAT1/STAT3 signaling in gefitinib-resistant non-small cell lung cancer." (PMID 31881805, 2019). "Intravenous delivery of the cyclic STAT3 decoy has been shown to potently inhibit the growth of both non-small cell lung cancer and head and neck cancer xenograft tumors." (PMID 31671769, 2019). "These aptamers significantly suppress the growth of human non-small cell lung cancer (NSCLC) tumors in vivo by selectively inhibiting the activation of Stat3 and its downstream proteins such as Bcl-2, Bcl-xL, Mcl-1, survivin, VEGF, Cyclin D1, and c-myc." (PMID 31640176, 2019). "Stat3 inhibitors are currently an important issue, as early clinical data has shown promising results in EGFR mutation- positive non-small cell lung cancer." (PMID 31690341, 2019). "The EGFR signaling pathway can also regulate PD-L1 expression through the IL-6/JAK/STAT3 pathway in non-small cell lung cancer (NSCLC) cells." (PMID 31480382, 2019). "recent work showed that the membrane bile acid receptor, TGR5, not only induces but also drives the growth and migration of non-small cell lung cancer cells by activating JAK2/STAT3 signaling." (PMID 31492006, 2019). "Studies suggest an miR-197-induced regulating mechanism of PD-L1 in tumor cells via the miR-197/CKS1B/STAT3 pathway in non-small cell lung cancer (NSCLC)." (PMID 29029502, 2017). "In this report, we further define a novel mechanism whereby YSY01A suppresses survival and migration of A549 non-small cell lung cancer cells by abrogating constitutively active STAT3 signaling cascade." (PMID 28883791, 2017). "The activation of both TrkB and STAT3 contribute to downstream signaling and promote human non-small-cell lung cancer proliferation." (PMID 27456333, 2016). "All the results indicated that activation of both STAT3 and TrkB was involved in the activation of Akt and the promotion of human non-small-cell lung cancer proliferation, with STAT3 and TrkB sharing the same regulation pathway." (PMID 27456333, 2016). "We correlated the expression of hamartin, p-TSC2 and p-mTOR with expression data concerning epidermal growth factor receptor mutations in non-small cell lung cancer and their influence on downstream Akt, MAPK and Stat3 signaling." (PMID 24593867, 2014). "Signal transducer and activator of transcription 3 (STAT3) is an important signaling mediator in malignant diseases and is persistently activated in 22%~65% of non-small cell lung cancers (NSCLC)." (PMID 24675568, 2014). "Uninvolved regional lymph node sections from 67 patients with stage I–III resected non-small cell lung cancer were immunostained to detect myeloid clusters, STAT3 activity and occult metastasis." (PMID 23717691, 2013). "Non-small-cell lung cancer patients with an activated JAK/STAT3 pathway are suitable cases for enzastaurin treatment." (PMID 22333600, 2012). "In this study we demonstrate that, as shown for many tumours, STAT3 is strongly phosphorylated in tumour tissue samples from patients with SCLC in comparison to samples from patients with NSCLC (non-small-cell lung cancer)." (PMID 19455144, 2009). "Constitutive activation of STAT3 correlates with cell proliferation in non-small-cell lung cancer (NSCLC) and also inhibits apoptosis." (PMID 17683579, 2007). "However, increased STAT3 signaling has been shown to increase UTX expression in an in vitro model of non-small cell lung cancer." (PMID 40065718, 2025). "Likewise, previous studies have indicated that miR-519a acts as a tumor suppressor in non-small cell lung cancer by regulating STAT3, thereby inhibiting tumor advancement." (PMID 40870875, 2025). "Another study reported the positive feedback loop between STAT3 and TNK2-AS1-mediated dysregulated STAT3 signaling by elevating VEGFA expression to facilitate angiogenesis in non-small cell lung cancer, indicating TNK2-AS1 as a potential target for therapeutic intervention." (PMID 38473229, 2024).
non-small cell lung carcinoma (continued). "The conclusion based on the experimental results was that STAT3 silenced non-small cell lung cancer (NSCLC) cells exhibit enhanced pro-inflammatory chemokine production, reduced MHCI antigen expression, and increased sensitivity to NK cell-mediated cytotoxicity." (PMID 38693304, 2024). "Furthermore, the inhibition of JAK1 with Anwulignan effectively suppresses the growth of non-small cell lung cancer by targeting the JAK1/STAT3 signaling pathway." (PMID 38921583, 2024). "Furthermore, ROS levels enhancing apoptosis in non-small cell lung cancer A549 and H1299 cells following treatment with raddeanin A were also reported to increase the phosphorylation of the STAT3 pathway." (PMID 38527038, 2024). "It has been shown that active growth factor receptors and non-receptor tyrosine kinases are associated with prolonged STAT3 activation in non-small cell lung cancer." (PMID 36852795, 2023). "Moreover, CAD-induced lysosomal H+ efflux sensitizes cancer cells to apoptosis induced by STAT3 inhibition and acts synergistically with STAT3 inhibition in restricting the tumor growth of A549 non-small cell lung carcinoma xenografts." (PMID 36807142, 2023). "Overall, we speculate that cinobufagin is a natural active ingredient with antitumor activity, which may exert an antitumor effect in non-small-cell lung cancer by blocking STAT3 signaling." (PMID 37928418, 2023). "Similarly, IL-17A strongly stimulates VEGF production and drives neovascular growth in animals via the STAT3/GIV signaling pathways in non-small-cell lung cancer." (PMID 36873773, 2023). "Furthermore, another study reported that ESM-1 expression was regulated via the JAK/STAT3 pathway in EGFR-activated non-small-cell lung cancer cells and induced by FoxO1 nuclear localization in cultured endothelial cells under hypoxic conditions." (PMID 36077661, 2022). "Sanguinarine inhibits cell proliferation and induces apoptosis by down-regulating JAK/STAT signaling pathway in non-small cell lung cancer, silencing STAT3 expression in non-small cell lung cancer, and further increasing Bax/Bcl-2 to promote cysteine The activity of winter enzyme can inhibit tumor." (PMID 36686745, 2022). "JAK/STAT3 pathway, suggested as a promising therapeutic strategy, was inhibited by physalin A, both by suppressing JAK receptor phosphorylation and preventing STAT3 translocation to the nucleus and, consequently, inhibiting its transcriptional activity in non-small lung cell carcinoma." (PMID 35450054, 2022). "Indeed, it has been reported that low doses of TRAIL promote tumor cell invasion and metastasis by activating p-STAT3 in non-small cell lung cancer and that TRAIL induces a significant amount of apoptosis in a human T-cell line in a dose-dependent manner." (PMID 34167551, 2021). "Gefitinib (Iressa) is an inhibitor of EGFR-tyrosine kinase that inhibits EGFR-dependent but not IL-6-dependent phosphorylation of STAT3, and is clinically used to treat non-small cell lung cancer patients with EGFR-activating mutations." (PMID 33392396, 2021). "In non-small cell lung cancer (NSCLC), secretion of oncostatin-M (OSM), a member of the IL-6 cytokine family, by cancer-associated fibroblasts increases STAT3 activity through activation of JAK1 and is a possible mechanism of resistance to targeted therapy such as EGFR and MEK inhibitors." (PMID 33521321, 2020). "Indeed, a previous study showed that PI3K/AKT inhibition induces compensatory activation of STAT3 in non-small cell lung cancer." (PMID 33299873, 2020). "Against the background of recent work demonstrating that garcinol inhibits CSCs-like phenotype of human non-small cell lung carcinoma by suppressing the Wnt/β-catenin/STAT3 signaling axis, we investigated the probable STAT signaling-mediated anti-GBM effect of garcinol." (PMID 31783691, 2019).